ZNF534 (zinc finger protein 534)
Description:
May be involved in transcriptional regulation.
Synonyms: KRBO3; FLJ25344
Tractability: PROTAC: ubiquitination databases record sites on it.
Gene: Protein-coding gene on chromosome 19 (52,429,148 to 52,452,315, forward strand). Ensembl gene ENSG00000198633.
Subcellular location: Nucleus
Subcellular location (Human Protein Atlas): Mitochondria
Pathways (Reactome):
Gene expression (Transcription): Regulation of endogenous retroelements by KRAB-ZFP proteins
Gene Ontology:
Molecular function: protein binding; DNA-binding transcription factor activity, RNA polymerase II-specific; RNA polymerase II cis-regulatory region sequence-specific DNA binding; sequence-specific double-stranded DNA binding
Biological process: regulation of transcription by RNA polymerase II; regulation of DNA-templated transcription
Cellular component: nucleus
Genetic constraint (gnomAD): Loss-of-function variants: 18 observed, 13.08 expected, observed/expected ratio (o/e) 1.38, 90% interval 0.94 to 1.88. The upper end of that interval is the gene's LOEUF score, 1.88, which puts it in group 6 of 6, group 1 being the genes least tolerant of losing a copy. Missense variants: 771 observed, 787.62 expected, observed/expected ratio (o/e) 0.98, 90% interval 0.92 to 1.04. Synonymous variants: 243 observed, 272.07 expected, observed/expected ratio (o/e) 0.89, 90% interval 0.8 to 0.99.
Homologues: Orthologues: chimpanzee ZNF534 (97% identical), macaque ZNF534 (70% identical). Paralogues in human: ZNF600 (48% identical), ZNF611 (48% identical), ZNF595 (46% identical), ZNF841 (46% identical), ZNF28 (45% identical), ZNF836 (44% identical), ZNF528 (44% identical), ZNF33B (44% identical), ZNF708 (43% identical), ZNF658 (43% identical), ZNF484 (43% identical), ZNF717 (42% identical), and 164 more.
Diseases named in the same sentence as ZNF534 in open-access papers:
ZNF534 is named in the same sentence as 2 diseases in open-access papers, as found by Europe PMC text mining. Sharing a sentence is not in itself a finding about the gene and the disease. The quoted sentences say what the papers report.
epithelioid mesothelioma (1 paper, 2022). "For example, the potential repressor ZNF534, which is particularly enriched in LTR7 and which is associated with pluripotency, is up-regulated in sarcomatoid compared with epithelioid mesothelioma." (PMID 36467966, 2022).
cancer (1 paper, 2019). A tumor composed of atypical neoplastic, often pleomorphic cells that invade other tissues. "Gene Ontology (GO) annotation for molecular function, biological processes and Reactome Pathways indicated that SP100 and USP45 are involved in DNA repair while ZNF534 is involved in DNA-templated regulation of transcription, making them good candidate cancer predisposing genes." (PMID 30947698, 2019).